CRTAC1 (cartilage acidic protein 1)
Diseases named in the same sentence as CRTAC1 in open-access papers (continued):
Sharing a sentence is not in itself a finding about the gene and the disease.
urothelial carcinoma (1 paper, 2025). A malignant neoplasm derived from the transitional epithelium of the urinary tract (urinary bladder, ureter, urethra, or renal pelvis). "In urothelial carcinoma, low CRTAC1 expression is significantly associated with high tumor stage, vascular invasion, and nodule metastasis." (PMID 40076501, 2025).
tumor (11 papers, 2021 to 2025). "Modulating the expression of CRTAC1 may effectively decrease tumor mutation load, suggesting that CRTAC1 could serve as a promising target for targeted therapy in LUAD." (PMID 38755183, 2024). "CRTAC1 exhibits the potential to function as both a diagnostic and prognostic biomarker, and it may hold significant implications for tumor immune microenvironment and drug therapy in LUAD." (PMID 38755183, 2024). "Additionally, as CRTAC1 expression decreased, there was a corresponding increase in tumor mutation load." (PMID 38755183, 2024). "Furthermore, we observed significant expression of CRTAC1 in the low-risk group, indicating its potential role as a tumor suppressor gene in BLCA." (PMID 37780567, 2023). "We also investigated the expression of CRTAC1 in tissues by IHC staining on tumor specimens from STS and LTS whose paired serum samples were analyzed by DIA‐MS." (PMID 40517318, 2025). "Consistently, we observed that CRTAC1 levels tended to be lower in paired tumor and serum samples from STS than in those from LTS." (PMID 40517318, 2025). "Several studies have reported that CRTAC1 upregulation inhibits tumor cell proliferation, invasion, and migration, as well as glycolysis and angiogenesis, and increases chemosensitivity." (PMID 40517318, 2025). "The result of WB confirmed the augmented protein expression of CRTAC1 in the adjacent normal tissue relative to the tumor tissue." (PMID 38755183, 2024). "The present study conducted a correlation analysis between the CRTAC1 expression and the immune cell infiltration as well as the presence of immune checkpoint genes within tumor immune microenvironment." (PMID 38755183, 2024). "In vivo mouse experiments showed that CRTAC1 overexpression increased the anti-tumor effects of cisplatin." (PMID 39596622, 2024). "The findings indicated that upregulation of CRTAC1 led to a decrease in cell proliferation, thereby demonstrating the tumor-suppressive properties of CRTAC1." (PMID 38755183, 2024). "According to the findings, TFAP2A expression was up-regulated in tumor tissue and negatively correlated with CRTAC1 expression (r = − 0.184, p < 0.001)." (PMID 38755183, 2024). "According to the outcomes of qPCR, the adjacent normal tissue had significantly higher mRNA levels of CRTAC1 than the tumor tissue." (PMID 38755183, 2024). "After cisplatin treatment, the mean NSCLC tumor size and weight were significantly lower in the CRTAC1 overexpression group than in the vector control group." (PMID 37633993, 2023). "Except CRTAC1 gene, other genes showed a higher expression level in the tumor group compared with the normal controls." (PMID 34238242, 2021). "The results showed that the expression levels of MS4A1 and KRT6A in tumour tissues were higher than in normal tissues, while CRTAC1 expression in tumour tissues was lower than in normal tissues." (PMID 34060213, 2021). "The gene expression results showed that the expression levels of MS4A1 and KRT6A in tumour tissues were higher than in normal tissues, while CRTAC1 expression in tumour tissues was lower than in normal tissues." (PMID 34060213, 2021). "CRTAC1 is expressed in tumor cells and in the extracellular matrix." (PMID 40517318, 2025). "The correlation of CRTAC1 levels between paired tumor and serum samples indicates that the low levels of circulating CRTAC1 may be due to reduced production of this protein by GB cells." (PMID 40517318, 2025). "Moreover, the results obtained from qPCR and WB experiments confirmed that the CRTAC1 expression level in tumor tissues exhibited a significant decrease in comparison to that of normal tissues." (PMID 38755183, 2024). "Additionally, qPCR and WB analyses showed that CRTAC1 expression was lower in tumor tissue compared to adjacent normal tissue at both the RNA and protein levels." (PMID 38755183, 2024). "CRTAC1, a pyroptosis-related gene, has been shown to be related to the development of tumor." (PMID 38755183, 2024).
tumor (continued). "Our analysis at the single-cell level has revealed that CRTAC1 is predominantly expressed in alveolar AT2 cells and minimally expressed in tumor cells, indicating that decreased CRTAC1 expression may be a significant factor in the oncogenic progression of epithelial cells." (PMID 38755183, 2024). "Although less research has been done on elastin Microfibril Interfacer 3 (EMILIN3) and cartilage acidic protein 1 (CRTAC1) in tumor immunity, previous findings suggest that CRTAC1 may influence the onset and progression of tumors by binding to calcium ions and innate immune pathways." (PMID 37405952, 2023). "In conclusion, this study demonstrated, for the first time, that CRTAC1 promotes cisplatin-dependent apoptosis in NSCLC and is a potential tumor molecular marker for predicting and improving cisplatin sensitivity in patients with NSCLC." (PMID 37633993, 2023). "The role of CRTAC1 in increasing the sensitivity of NSCLC cells to cisplatin was confirmed in vitro and in vivo by constructing cell and animal tumor-bearing models." (PMID 37633993, 2023). "Cartilage acidic protein 1 (CRTAC1), an extracellular matrix protein, could be a tumor suppressor." (PMID 40076501, 2025). "Additionally, CYP4F8, PDZD3, CRTAC1, and LRTM1 were identified as potential tumor suppressor genes." (PMID 38172792, 2024).
cancer (6 papers, 2015 to 2025). A tumor composed of atypical neoplastic, often pleomorphic cells that invade other tissues. "Additionally, our study indicated that CRTAC1 expression correlated positively with the majority of immune checkpoint genes in diverse cancer types." (PMID 38755183, 2024). "The mRNA expression levels of CRTAC1 were significantly decreased in LUAD and various other types of cancer (p < 0.05)." (PMID 38755183, 2024). "Our research revealed a significant elevation in the DNA methylation level of CRTAC1 in LUAD tissue relative to normal tissue, suggesting the potential role of CRTAC1 in cancer suppression." (PMID 38755183, 2024). "CRTAC1, HRG, and IL1R2 are not cancer‐specific biomarkers, but they are broadly associated with various diseases." (PMID 40517318, 2025). "The expression of CRTAC1, DUSP2, ATOH8, and HIST2H2AC showed a significantly negative correlation with the activity of most hallmark-cancer pathways." (PMID 33604353, 2020). "The detailed mechanisms of action of CRTAC1, HRG, and IL1R2 in cancer progression are not yet fully established." (PMID 40517318, 2025).
infection (2 papers, 2023). The state of being infected such as from the introduction of a foreign agent such as serum, vaccine, antigenic substance or organism. "Decreased plasma CRTAC1 could result from decreased production as occurs with ALB and TTR, increased turnover as occurs during severe infection with GSN serving as a scavenger for filamentous actin being released from cells, or a combination of mechanisms." (PMID 37667413, 2023).
CRTAC1 also shares sentences with these, for which no sentence is quoted: atherosclerosis (2 papers); Anosmia (1); breast carcinoma (1); cardiovascular diseases (1); colon adenocarcinoma (1); lung squamous cell carcinoma (1); psoriasis (1); pulmonary arterial hypertension (1); pulmonary embolism (1); rheumatoid arthritis (1); Stroke (1); thyroid tumor (1).